TUBG1 (tubulin gamma 1)
Description:
Tubulin is the major constituent of microtubules, protein filaments consisting of alpha- and beta-tubulin heterodimers. Gamma-tubulin is a key component of the gamma-tubulin ring complex (gTuRC) which mediates microtubule nucleation. The gTuRC regulates the minus-end nucleation of alpha-beta tubulin heterodimers that grow into microtubule protafilaments, a critical step in centrosome duplication and spindle formation. Plays a role in sperm morphological development during late stage spermiogenesis, particularly the anchoring of the sperm head to the tail.
Synonyms: GCP-1; TUBG; TUBGCP1; CDCBM4
Tractability: Small molecule: a structure with a bound ligand is known; it has a high-quality binding pocket; it belongs to a druggable protein family. PROTAC: ubiquitination databases record sites on it; its protein half-life has been measured.
Gene: Protein-coding gene on chromosome 17 (42,609,637 to 42,615,241, forward strand). Ensembl gene ENSG00000131462.
Subcellular location: Cytoplasm, cytoskeleton, microtubule organizing center, centrosome; Cytoplasm, cytoskeleton, spindle
Subcellular location (Human Protein Atlas): Principal piece
Pathways (Reactome):
Cell Cycle: AURKA Activation by TPX2; Loss of Nlp from mitotic centrosomes; Loss of proteins required for interphase microtubule organization from the centrosome; Recruitment of NuMA to mitotic centrosomes; Recruitment of mitotic centrosome proteins and complexes; Regulation of PLK1 Activity at G2/M Transition
Organelle biogenesis and maintenance: Anchoring of the basal body to the plasma membrane
Gene Ontology:
Molecular function: identical protein binding; protein binding; GTP binding; microtubule nucleator activity; structural constituent of cytoskeleton
Biological process: spermatid development; meiotic spindle organization; microtubule cytoskeleton organization; microtubule nucleation; mitotic cell cycle; mitotic sister chromatid segregation; mitotic spindle organization; cytoplasmic microtubule organization; microtubule-based process
Cellular component: centrosome; cytoplasm; mitotic spindle microtubule; polar microtubule; recycling endosome; condensed nuclear chromosome; cytosol; gamma-tubulin complex; gamma-tubulin ring complex; spindle; apical part of cell; cell leading edge; centriole; ciliary basal body; cilium; cytoplasmic microtubule; microtubule; microtubule organizing center; non-motile cilium; pericentriolar material; spindle microtubule
Genetic constraint (gnomAD): Loss-of-function variants: 22 observed, 53.93 expected, observed/expected ratio (o/e) 0.41, 90% interval 0.29 to 0.58. The upper end of that interval is the gene's LOEUF score, 0.58, which puts it in group 2 of 6, group 1 being the genes least tolerant of losing a copy. Missense variants: 217 observed, 615.36 expected, observed/expected ratio (o/e) 0.35, 90% interval 0.31 to 0.4. Synonymous variants: 198 observed, 235.72 expected, observed/expected ratio (o/e) 0.84, 90% interval 0.75 to 0.94.
Gene-disease validity (ClinGen):
ClinGen rates the evidence that TUBG1 causes each of these diseases.
lissencephaly spectrum disorders (autosomal dominant): Definitive.
Homologues: Orthologues: chimpanzee TUBG1 (100% identical), dog TUBG1 (99% identical), mouse Tubg1 (99% identical), rat Tubg1 (99% identical), guinea pig TUBG1 (99% identical), tropical clawed frog tubg1 (98% identical), zebrafish tubg1 (98% identical), pig TUBG1 (88% identical), macaque TUBG1 (87% identical), rabbit TUBG1 (87% identical), Drosophila melanogaster gammaTub23C (79% identical). Paralogues in human: TUBG2 (98% identical), TUBB4B (35% identical), TUBB8 (35% identical), TUBB3 (35% identical), TUBB8B (35% identical), TUBB2A (35% identical), TUBB2B (35% identical), TUBB4A (35% identical), TUBB (35% identical), TUBB6 (35% identical), TUBB1 (33% identical), TUBA1C (31% identical), and 11 more.
Diseases named in the same sentence as TUBG1 in open-access papers:
TUBG1 is named in the same sentence as 47 diseases in open-access papers, as found by Europe PMC text mining. Sharing a sentence is not in itself a finding about the gene and the disease. The quoted sentences say what the papers report.
microcephaly (7 papers, 2018 to 2024). A congenital or acquired developmental disorder in which the circumference of the head is smaller than normal for the person's age and sex. "TUBG1 mutations have been linked to a spectrum of cortical malformations, including microcephaly, polymicrogyria, pachygyria, and agyria." (PMID 38919239, 2024). "Tubulinopathies result from mutations in tubulin genes, including TUBG1, responsible for cell microtubules, are characterized by brain development abnormalities, microcephaly, early-onset epilepsy, and motor impairment." (PMID 31151415, 2019). "Variants in TUBG1 have been described in three patients with posterior predominant pachygyria and microcephaly." (PMID 29706637, 2018). "Most patients with variants in TUBG1 also exhibit microcephaly, indicating a major role of TUBG1 in neuronal cell proliferation." (PMID 29706637, 2018). "Microtubule structure alterations as well as alterations of binding partners necessary for proper microtubule dynamics resulting from pathogenic variants in TUBA1A, TUBB2A, TUBB2B, TUBB3, TUBB5, TUBG1 and TUBA8 genes are also responsible microcephaly and microlissencephaly." (PMID 30340542, 2018). "The association between microcephaly, polymicrogyria and cerebellar agenesis prompted us to screen for tubulin genes (TUBA1A, TUBA8, TUBB2A, TUBB2B, TUBB3, TUBB4A, TUBB, TUBG1), which were all negative." (PMID 35162247, 2022).
tubulinopathies (7 papers, 2017 to 2025). "Mutations in seven genes encoding α- (TUBA1A), β- (TUBB2A, TUBB2B, TUBB3, TUBB4A, TUBB5), and γ- (TUBG1) microtubulin are linked to extensive overlapping brain malformations or tubulinopathies." (PMID 40948494, 2025). "Other “tubulinopathies” genes include TUBA1A, TUBB2A, TUBB2B, TUBA8, TUBB3, TUBB, and TUBG1, which were found to be DEGAs in various brain regions." (PMID 34638726, 2021).
breast carcinoma (6 papers, 2011 to 2025). "The TUBG1 gene has been associated with the risk of breast cancer." (PMID 35844396, 2022). "Conversely, an interaction between rs299290 and rs11649877 (3’ region of TUBG1) could increase breast cancer risk in both BRCA1 and BRCA2 mutation carriers (HRs = 1.33 and 1.21, respectively)." (PMID 25830658, 2015). "In addition to the main effects, interaction between HMMR and AURKA, and between HMMR and TUBG1 could influence breast cancer risk in BRCA1 and BRCA2 mutation carriers." (PMID 25830658, 2015). "Similarly, earlier studies have reported high expression levels of TUBG1 in breast cancer, non-small cell lung cancer, and medulloblastomas." (PMID 36523478, 2022). "While the HMMR association study in BRCA1/2 mutation carriers drew on a partial dataset from the Consortium of Investigators of Modifiers of BRCA1/2 (CIMBA), the depicted mechanistic model highlighted additional gene candidates for breast cancer risk; i.e., AURKA, TPX2, and TUBG1." (PMID 25830658, 2015). "Furthermore, variation in TUBG1 was found to be associated with breast cancer risk in a hospital-based case-control study, but has not been assessed in BRCA1/2 mutation carriers." (PMID 25830658, 2015).
epilepsy (5 papers, 2019 to 2024). A brain disorder characterized by episodes of abnormally increased neuronal discharge resulting in transient episodes of sensory or motor neurological dysfunction, or psychic dysfunction. "De novo heterozygous missense variants in the γ-tubulin gene TUBG1 have been linked to human malformations of cortical development associated with intellectual disability and epilepsy." (PMID 31086189, 2019). "Epilepsy is another clinical feature commonly shared by patients with TUBG1 mutations." (PMID 38919239, 2024). "Therefore, a complete diagnosis of TUBG1 mutation-associated cortical malformation (lissencephaly/pachygyria) with microcephaly and early-onset epilepsy was established." (PMID 38912084, 2024). "Hence, a complete diagnosis of TUBG1 mutation-associated cortical malformation (lissencephaly/pachygyria) with microcephaly and early-onset epilepsy was established." (PMID 38912084, 2024).
brain malformations (4 papers, 2018 to 2025). "TUBG1-associated brain malformations appear to result from a gain-of-function mechanism as only missense variants have been reported to date (n = 10) associated with brain malformations." (PMID 36672848, 2022). "In addition, a single nucleotide mutation in the MCR of TUBG1 leads to complex cortical dysplasia with other brain malformations (CDCBM), including aberrant neuronal migration and disrupted axonal guidance." (PMID 32827758, 2020). "γ-Tubulin expression is altered in various malignancies, and changes in the TUBG1 gene have been found in patients suffering from brain malformations." (PMID 30221013, 2018).
Lissencephaly (4 papers, 2022 to 2026). A spectrum of malformations of cortical development caused by insufficient neuronal migration that subsumes the terms agyria, pachygyria and subcortical band heterotopia. "Here, we report a case of missense mutation in the TUBG1 gene, which led to lissencephaly presenting with epileptic spasms, spasticity, microcephaly, and global developmental delay." (PMID 38912084, 2024).
cortical dysplasia (3 papers, 2015 to 2020). "Polymicrogyria or polymicrogyria-like cortical dysplasia and a simplified gyral pattern, which is common in TUBB2B and TUBB3 variants, have not been described in patients with TUBG1 variants so far." (PMID 29706637, 2018).
hepatocellular carcinoma (3 papers, 2022 to 2025). A malignant tumor that arises from hepatocytes. "Correlation between TUBG1 expression and clinicopathological characteristics in HCC (n = 371) TUBG1, tubulin gamma 1; HCC, hepatocellular carcinoma." (PMID 36523478, 2022).
Intellectual disability (3 papers, 2019 to 2024). "A previous patient with a TUBG1 mutation did not have an apparent intellectual disability until six years of age." (PMID 38919239, 2024). "Phenotypic features shared by most of the patients with TUBG1 mutations include moderate to severe intellectual disability, motor impairment, and speech delays ranging from nonverbal to moderately delayed speech." (PMID 38919239, 2024).
breast tumors (2 papers, 2015 to 2022). "Combined expression of HMMR and AURKA, and HMMR and TUBG1 in sporadic breast tumors appeared to influence patients’ survival differentially." (PMID 25830658, 2015). "Following these suggestions, the expression of HMMR and AURKA or TUBG1 in sporadic breast tumors was found to potentially interact, influencing patients’ survival." (PMID 25830658, 2015).
osteosarcoma (2 papers, 2021 to 2025). A usually aggressive malignant bone-forming mesenchymal neoplasm, predominantly affecting adolescents and young adults. "We gene-edited various cell lines, including A549 (adenocarcinomic alveolar basal epithelia) and U2OS (human osteosarcoma) cells, using a green fluorescence tagged Cas9- TUBG1-sg gene." (PMID 40013266, 2025).
endometrial cancer (1 paper, 2019). Primary or metastatic malignant neoplasm involving the endometrium (mucous membrane that lines the endometrial cavity). "In an extensive study that compared PTX with eribulin (ERB, a microtubule destabilizer) treatment of many breast, ovarian, and endometrial cancer cell lines, we confirmed differential regulation of all expressed TUBAs and TUBBs and TUBG1." (PMID 30964857, 2019).
heart failure (1 paper, 2016). Inability of the heart to pump blood at an adequate rate to meet tissue metabolic requirements. "Supporting the notion that the tubulin network is distorted in heart failure cells, mRNA expression analysis by qPCR confirmed an overall increase in the expression of α1A-tubulin (TUBA1A), β2B-tubulin (TUBB2B), β3-tubulin (TUBB3), γ-1tubulin (TUBG1), and microtubule-associated proteins (MAP4)." (PMID 26725114, 2016).
melanoma (1 paper, 2022). A malignant, usually aggressive tumor composed of atypical, neoplastic melanocytes. "The most significant differences in melanoma are NOMO1, PIGT, VKORC1, PDIA5 and DDX11, and the most significant differences in uterine cancer are CTU2, EMC8, TUBG1, CLPP and LONP1." (PMID 34951103, 2022).
nematode infections (1 paper, 2018). "After initial up-regulation, expression of TUBG1 and TUBG2 is significantly down-regulated in mature syncytia, but lack of expression of either of γ-tubulin genes reduces numbers of nematode infections and developing females." (PMID 29947953, 2018). "Herein, we show that although the expression of TUBG1 and TUBG2 genes changes from up-regulation during early stages of syncytium development till down-regulation in mature syncytia, the presence of both γ-tubulin isoforms has fundamental importance for nematode infection and female development." (PMID 29947953, 2018).
Nystagmus (1 paper, 2024). Rhythmic, involuntary oscillations of one or both eyes related to abnormality in fixation, conjugate gaze, or vestibular mechanisms. "Our patient presented with unique additional phenotypic characteristics not previously reported among other patients with TUBG1 mutations, such as trigonocephaly, nystagmus, scoliosis, and a tethered frenulum." (PMID 38919239, 2024).
tumor (9 papers, 2013 to 2023). "In in vitro cellular assay, γ-tubulin was reported to form a complex with proliferating cell nuclear antigen (PCNA), and a significant correlation in expression of γ-tubulin (TUBG1) with PCNA was reported in tumor cells." (PMID 37466845, 2023). "In patients with HCC, high TUBG1 expression levels were significantly related to clinical stage (P < 0.001), tumor status (stage T, P = 0.004), race (P < 0.001), and vital status (P = 0.006)." (PMID 36523478, 2022). "The most common types were gain and diploid, and the expression abundance of TUBG1 was closely related to tumor prognosis." (PMID 36523478, 2022). "To test a possible synergism of PCNA and γ-tubulin in the maintenance of indefinite proliferation and development of cancer, we evaluated a potential interrelationship between PCNA and TUBG1 in different tumor types." (PMID 34158617, 2021). "At the same time, its expression was related to the clinical stage, race, and survival status of the tumor, suggesting that high expression levels of TUBG1 may lead to poor prognoses." (PMID 36523478, 2022). "In addition, γ-synuclein affects centrosome components γ-tubulin (TUBG1) and Δ-tubulin (TUBD1) which are associated with tumorigenesis and tumor progression." (PMID 24040069, 2013). "Among them, ACAA1, GART, PDE9A, RPL3, TUBA1A, and TUBG1 gene products interact with several proteins known to be involved in the PRAD pathway and particularly important for apoptosis inhibition and tumor growth." (PMID 33712625, 2021). "EZH2, TUBG1, and PPM1G are related to the ferroptosis gene, FANCD2, and may be involved in tumor biological behaviors mediated by ferroptosis." (PMID 36686830, 2022). "Consistent with our hypothesis, we found a significant positive correlation between TUBG1 and PCNA expression in all the datasets we examined (33 tumor subtypes, N = 9,664)." (PMID 34158617, 2021).
cancer (7 papers, 2015 to 2025). A tumor composed of atypical neoplastic, often pleomorphic cells that invade other tissues. "Given these compensatory mechanisms, TUBG1-targeting strategies may hold therapeutic potential for disorders involving cytoskeletal dysfunction, such as certain types of cancer, neurodegeneration, and aging." (PMID 40013266, 2025). "In addition, the use of γ-tubulin to predict BRCA status showed sensitivity of 83% and specificity of 89%, suggesting that TUBG1 is a promising diagnostic biomarker for HCC and has potential value for diagnosing other cancers." (PMID 36523478, 2022). "Tubulin gamma 1 (TUBG1) plays an oncogenic role in several human cancers; however, its functional role in HCC tumorigenesis remains unknown." (PMID 36523478, 2022). "The pan-cancer analysis results suggest that the eight hub genes (TXNRD1, TUBG1, SF3B4, PPM1G, PIGU, NDRG1, GRPEL2, and EZH2) were differentially expressed in gastrointestinal tumors." (PMID 36686830, 2022). "However, only five similar proteins were identified in all three cancer cell lines and these include SSSCA1 as expected, Tankyrase 1 (TNKS1), γ-tubulin (TUBG1), and the poorly characterized rRNA methyltransferase MRM2 and membrane associated VAPA." (PMID 32170109, 2020).
infection (2 papers, 2011 to 2018). The state of being infected such as from the introduction of a foreign agent such as serum, vaccine, antigenic substance or organism. "Transcription analyses demonstrate augmentation of the γ-tubulin (TUBG1 and TUBG2) and two γ-tubulin-complex protein genes (GCP3 and GCP4) in the course of infection with root-knot nematodes in galls." (PMID 22144887, 2011). "Moreover, taking into consideration the lack of TUBG1 and TUBG2 redundancy in infection tests, our novel results rise serious concerns if both γ-tubulin proteins do really play the same roles in plant cells." (PMID 29947953, 2018).
TUBG1 also shares sentences with these, for which no sentence is quoted: Pachygyria (4 papers); lung carcinoma (3); polymicrogyria (3); medulloblastoma (2); bladder (1); breast (1); cerebellar agenesis (1); cholangiocarcinoma (1); colorectal cancer (1); complex cortical dysplasia with other brain malformations (1); craniosynostosis (1); early-onset epilepsy (1); Epstein-Barr virus infection (1); gastrointestinal tumors (1); microlissencephaly (1); multiple myeloma (1); neurodevelopmental disorder (1); non-alcoholic fatty liver disease (1); non-small cell lung carcinoma (1); ovarian carcinoma (1); pancreatic cancer (1); Primary microcephaly (1); prostate carcinoma (1); schizencephaly (1); tethered spinal cord syndrome (1); trigonocephaly (1); uterine cancer (1); virus infection (1).